IL17A (interleukin 17A)
Diseases named in the same sentence as IL17A in open-access papers (continued):
Sharing a sentence is not in itself a finding about the gene and the disease.
orchitis (2 papers, 2021 to 2024). Inflammation of one or both testes due to viral or bacterial infections. "In this study, the mRNA expressions of IL-2, TNF-α, IL-17A, and IL-1β, which have essential roles in inflammatory processes, were elevated in LPS-induced orchitis; however, PHN have been found to reduce their expression." (PMID 38846786, 2024).
overactive bladder (2 papers, 2022). Symptom of overactive detrusor muscle of the urinary bladder that contracts with abnormally high frequency and urgency. "The cytokines with high diagnostic values to distinguish IC/BPS and overactive bladder included IL-10, RANTES, eotaxin, CXCL10, IL-12p70, NGF, IL-6, IL-17A, MCP-1, and IL-1RA." (PMID 35626252, 2022). "Using different urinary biomarkers including IL-10, RANTES, eotaxin, CXCL10, IL-12p70, NGF, IL-6, IL-17A, MCP-1, and IL-1RA, IC/BPS could be distinguished from overactive bladder." (PMID 36233356, 2022).
pancolitis (2 papers, 2015 to 2022). Ulcerative colitis that involves the entire colon. "In the hosts the donor T cells cause pancolitis and small bowel inflammation mediated by cytokines such as INFγ and IL-17A." (PMID 36389671, 2022).
post-traumatic stress disorder (2 papers, 2022). An anxiety disorder precipitated by an experience of intense fear or horror while exposed to a traumatic (especially life-threatening) event. "For example, inflammatory signals like interleukin 17A serum levels in a murine model of posttraumatic stress disorder modulate DCX and Ki67+cells in the DG or extracellular and adhesion molecules can promote alertness and activation of NSCs in response to indicators that affect the entire organism." (PMID 36407114, 2022).
posterior uveitis (2 papers, 2011 to 2024). Inflammation of the choroid as well as the retina and vitreous body. "Knowledge concerning the mechanisms whereby IL-17A regulates the secretion of inflammatory mediators by RPE cells may increase our insight in the pathogenesis of posterior uveitis and delineating the transactivation mechanisms may help to identify new therapeutic targets." (PMID 22162626, 2011).
premature ovarian failure (2 papers, 2022 to 2024). "In addition, it was found that IL-17A/IL-6 axis expression was up-regulated in a cyclophosphamide (CTX)-induced model of premature ovarian failure in rats, significantly regulating the activities of REK1/2 and MEK1/2." (PMID 39568012, 2024).
pressure ulcer (2 papers, 2013 to 2021). "In this report, we used a pressure ulcer (PU) model in ob/ob mice to show that compromised diabetic wound repair correlates with decreased expression of KLF4 and upregulation of IL-17A." (PMID 34568499, 2021). "In this report, using an ob/ob mouse pressure ulcer model, we demonstrated that KLF4-regulated MDSCs promoted diabetic wound healing by suppressing Th17 differentiation and subsequent IL-17A expression." (PMID 34568499, 2021).
Pseudomonas infection (2 papers, 2020 to 2021). Infections with bacteria of the genus pseudomonas. "In fact, IL-17a impairs host tolerance in chronic Pseudomonas infection." (PMID 32823681, 2020).
pterygium (2 papers, 2024 to 2025). A wedge-shaped fibrovascular lesion arising from the bulbar conjunctiva and extending to the cornea. "Gene expression analysis revealed significant overexpression of inflammatory genes in the pterygium, with differences up to 24.7-fold for IL17A (p < 0.05) and 2.8-fold for TNF-α (p < 0.05) compared to healthy conjunctiva." (PMID 40806545, 2025).
Pulmonary hemorrhage (2 papers, 2025 to 2026). Pulmonary hemorrhage is a bleeding within the lungs. "In 4T1 models, B. lactis V9 co-therapy mitigated αPD-1-induced uterine inflammation and pulmonary hemorrhage by downregulating IL-1α, IL-1β, and IL-17A while maintaining effector cytokines." (PMID 42273689, 2026).
radiation pneumonitis (2 papers, 2014 to 2018). Inflammation of the lung due to harmful effects of ionizing or non-ionizing radiation. "There was no significant change of IL-17A concentration before and after radiotherapy in radiation pneumonitis group, but after radiotherapy IL-17A concentration in serum were remarkably higher than that in non-radiation pneumonitis group (P < 0.05)." (PMID 29764588, 2018). "Recent studies have reported that TGF-β, IL6, IL-1β, and TNF-α are not only closely involved in radiation pneumonitis but also regulate IL-17A release from Th17 cells." (PMID 24744681, 2014). "On the basis of strictly controlling radiation dose on normal tissue, IL-17A in serum could be the predictive factors of radiation pneumonitis for local advanced NSCLC patients with concurrent chemoradiotherapy." (PMID 29764588, 2018). "Indeed, the further experimental studies should be carried out by using IL-17A knockout mice or IL-17A antagonist to study radiation pneumonitis and fibrosis, thus establishing the direct evidence of IL-17A in radiation-induced lung injury." (PMID 24744681, 2014). "Correlation analysis found that the change of ICAM-1 before and after radiotherapy has no obvious correlation with the incidence of radiation pneumonitis, and IL-17A change has obvious correlation with the incidence of radiation pneumonitis." (PMID 29764588, 2018).
retinal degeneration (2 papers, 2013 to 2014). Degeneration of the retina. "The ultimate goal of the present study was to evaluate the therapeutic potential of IL17A knockdown in a preclinical retinal degeneration model." (PMID 24780906, 2014). "Subsequently, we noted that the anti-inflammatory agent TSG-6 halted Ccl2−/−/Cx3cr1−/−/Crb1rd8 (DKO/rd8) retinal degeneration and found that treated retinas expressed less Il17a." (PMID 24780906, 2014). "We hypothesized that IL17A neutralization could prevent retinal degeneration in DKO/rd8." (PMID 24780906, 2014). "Importantly, knockdown of Il-17a did not prevent or improve rd8 retinal dystrophy, suggesting IL-17A to be a specific target for AMD-like retinal degenerative disease and highlighting the phenotype of DKOrd8 to be that of retinal degeneration rather than retinal dystrophy alone." (PMID 24432192, 2013).
Strabismus (2 papers, 2017 to 2021). A misalignment of the eyes so that the visual axes deviate from bifoveal fixation. "We found the expression of INF-γ, IL-10, IL-12p70, and IL-17A in tears of strabismus patients, which were no significantly higher than those of normal subjects, while IL-6 and TNF-α were statistically significant." (PMID 34659636, 2021).
Strongyloides infection (2 papers, 2021 to 2022). "A diminution in mycobacterial-specific Th1 cells and Th17 cells and their relevant cytokines (i.e., IFN-γ, TNF-α and IL-2, IL-17A, and IL-17F) has been found in patients with concomitant filarial or Strongyloides infection." (PMID 34202662, 2021).
Subglottic stenosis (2 papers, 2019 to 2022). "The canonical IL-23/IL-17A pathway is activated in the tracheal mucosa of idiopathic subglottic stenosis patients." (PMID 35902909, 2022). "Further advances in molecular technologies have allowed for investigations of mucosal inflammatory factors, revealing an aberrant upregulation in inflammatory pathway interleukin-17A (IL-17A)/IL-23 within idiopathic subglottic stenosis mucosa." (PMID 31043518, 2019).
T-cell immunodeficiency (2 papers, 2024 to 2025). A broad classification of disorders that affect the cell-mediated aspect of the immune response. "Thus, our study revealed that PmA induced T-cell immunodeficiency, and that the activation of Th17 cells/IL-17A via the IL-6–JAK2–STAT3 axis was a key mechanism against PmA." (PMID 41402924, 2025).
tinea (2 papers, 2024). "We present an unusual case of tinea corporis and faciei caused by Trichophyton tonsurans that developed after starting the IL-17A/F inhibitor bimekizumab." (PMID 39634792, 2024).
tongue cancer (2 papers, 2017 to 2022). A malignant neoplasm affecting the tongue. "Pearson's correlation coefficient analysis revealed that expression of IL-17A was reversely correlated with expression of miR-23b (r = -0.316; P < 0.05) in all 63 tongue cancer samples." (PMID 28035060, 2017).
toxocariasis (2 papers, 2021 to 2022). A parasitic infection caused by worms found in domestic animals. "Finally, future studies are needed to reveal the mechanisms of pharmacological modulation of IL-17A during the parasite-host relationship in the context of toxocariasis." (PMID 35844540, 2022).
Tracheomalacia (2 papers, 2019 to 2021). "The expression of cytokines, IL-8, IL17A, and IL-1α, is higher in patients affected by tracheomalacia, and this has the potential to indicate the presence of chronic airway inflammation and also lung microbiota disequilibrium, with a prevalence of Pseudomonas at the BALF." (PMID 34356592, 2021).
trigeminal neuralgia (2 papers, 2021 to 2022). Trigeminal neuralgia is a nerve disorder that causes a stabbing or electric-shock-like pain in parts of the face. "In the present study patients with trigeminal neuralgia showed lower levels of growth factor levels such as Ang-2, bFGF, HGF, SCF, TGF-α, and VEGF and higher cytokine levels of IL-1β, TNF-α, CCL2, IL-17A, IL-6, and CXCL8 in comparison with normal individuals." (PMID 34067581, 2021).
ventilator-associated pneumonia (2 papers, 2017 to 2019). Serious INFLAMMATION of the LUNG in patients who required the use of PULMONARY VENTILATOR. "In this study we examine the relationship between alveolar Th17 cells, alveolar IL-17A and the presence of ventilator associated pneumonia." (PMID 28806403, 2017). "We also show that, as previously reported, IL-17A is likely responsible for increased alveolar leak and neutrophil recruitment, yet the source of IL-17A protein in ventilator associated pneumonia is currently unknown." (PMID 28806403, 2017). "Taken together, these findings suggest that while there are several putative roles for IL-17A in pulmonary infection, that these mechanisms are likely independent of Th17 cell function in ventilator associated pneumonia." (PMID 28806403, 2017).
xerostomia (2 papers, 2023 to 2024). Dryness of the mouth resulting from reduced salivary secretion. "Among the inflammatory cytokines assessed - IL-6, TNF-α, IFN-γ, IL-10, IL-12p70, IL-1β, IL-8, IL-13, IL-2, IL-5, IL-7 and IL-17A, xerostomia correlated with lower levels of saliva IL-2 and TNF-α, and elevated levels of serum IL-12p70 and IL-10 (p < 0.05)." (PMID 36846089, 2023).
AA amyloidosis (1 paper, 2022). Secondary amyloidosis is a form of amyloidosis, that complicates chronic inflammatory disorders (mainly rheumatoid arthritis) and is characterized by the aggregation and deposition of amyloid fibrils composed of serum amyloid A protein, an acute phase reactant. "Additionally, we report the first case with successful treatment outcome by using a monoclonal antibody against IL-17A, secukinumab in a patient with refractory PsA and AA amyloidosis." (PMID 36128216, 2022).
actinomycete infections (1 paper, 2019). "In the M. bovis infection model it was demonstrated that IL-17A deficient mice showed impaired granuloma formation, indicating the importance of IL-17A in establishing granuloma’s around actinomycete infections." (PMID 31295246, 2019).
actinomycetoma (1 paper, 2019). "Unlike IL-17A expression, we did found differences in MMP-9 expression between M. mycetomatis and the actinomycetoma lesions A. pelletierii and S. somaliensis." (PMID 31295246, 2019).
amnesia (1 paper, 2023). Pathologic partial or complete loss of the ability to recall past experiences ( AMNESIA, RETROGRADE) or to form new memories ( AMNESIA, ANTEROGRADE). "Therefore, we investigated whether we could reverse the effect of MIA on infantile amnesia in the offspring through the administration of IL-17a at the time of memory encoding (P17) or memory recall (P25)." (PMID 37939176, 2023). "Postnatal immune activation in C57BL/6 J male mice did not affect infantile amnesia, indicating that there is a critical window during prenatal development where IL-17a and immune activation can affect a mammal’s propensity for infantile amnesia." (PMID 37939176, 2023). "Having established that immune activation and direct administration of the downstream cytokine Il-17a are sufficient to induce altered infantile amnesia, we next sought to test whether Il-17a is necessary for this effect to occur." (PMID 37939176, 2023). "Regardless of whether injected with IL-17a or PBS, MIA male infant offspring showed normal memory retention for a CFC memory 8 days after training, indicating that the effect of MIA on infantile amnesia cannot be reversed through acute IL-17a administration." (PMID 37939176, 2023). "Preventing maternal IL-17a signaling, using a genetic model, occluded the MIA effect on infantile amnesia in the offspring." (PMID 37939176, 2023). "Last, we show that the downstream cytokine, IL-17a, is both sufficient and necessary for the effect of MIA on infantile amnesia." (PMID 37939176, 2023). "Like contextual fear memory, male offspring from poly(I:C)- or IL-17a–injected dams do not show infantile amnesia for an object memory." (PMID 37939176, 2023).
aniridia (1 paper, 2020). Aniridia is a congenital ocular malformation characterized by the complete or partial absence of the iris. "Tear IL-17A levels were significantly greater in various ocular surface inflammatory diseases (including SS, not SS-DED, MGD, aniridia and oGVHD) as compared to control subjects, supporting a role for IL-17A in the immune pathogenesis of DED." (PMID 32354090, 2020).
aortitis (1 paper, 2019). Inflammation of the aorta. "Here, we demonstrate that IL-25 plays a facilitative role in the development of IL-1–, TNF– and IL-17A–mediated aortitis in Il1rn−/− mice." (PMID 31745167, 2019). "Mice deficient in IL-1 receptor antagonist (Il1rn−/− mice) have excessive IL-1 signaling, resulting in spontaneous development of IL-1–, TNF– and IL-17A–dependent aortitis." (PMID 31745167, 2019). "In our model, IL-25 deficiency resulted in reduced expression of Il17a and Tnfa mRNA in the aortae of Il1rn−/− mice, suggesting that IL-25 somehow enhanced the development of IL-1–, TNF– and IL-17–mediated aortitis in Il1rn−/− mice." (PMID 31745167, 2019). "IL-25 enhanced IL-1β and TNF production by IL-25 receptor–expressing dendritic cells and macrophages, respectively, at inflammatory sites of aortae of Il1rn−/− mice, contributing to exacerbation of development of IL-1–, TNF– and IL-17A–dependent aortitis in those mice." (PMID 31745167, 2019). "We found that expression of II25 mRNA was increased in the aortae of Il1rn−/− mice, suggesting that IL-25 may suppress development of IL-1–, TNF– and IL-17A–dependent aortitis in Il1rn−/− mice by inhibiting type 3-mediated immune responses." (PMID 31745167, 2019). "Th17 cell-derived IL-17A contributes to development of aortitis in Il1rn−/− mice." (PMID 31745167, 2019). "However, the role of IL-25 in IL-1–, TNF– and IL-17A–mediated aortitis in Il1rn−/− mice has been unclear." (PMID 31745167, 2019). "T cells and IL-17A are also known to be important for development of aortitis in Il1rn−/− mice." (PMID 31745167, 2019). "The spontaneous development of aortitis in those Il1rn−/− mice was dependent on T cells, whereas it was suppressed by deficiency of TNF-α or IL-17A, but not IL-622,23." (PMID 31745167, 2019). "On the other hand, our results suggest that IL-25 may enhance production of IL-6, IL-17A and TNF, but not IL-23, thereby contributing to development of IL-1–, TNF– and IL-17A–dependent aortitis in Il1rn−/− mice." (PMID 31745167, 2019).
arteriovenous malformations (1 paper, 2013). "A possible link between CNS vascular pathology and IL-17A has recently been published demonstrating an association between bleedings from arteriovenous malformations and a polymorphism in the IL-17A gene in human." (PMID 23468966, 2013).
Autosomal dominant hyper-IgE syndrome (1 paper, 2017). 2000 IU/ml), recurring staphylococcal skin abscesses, and recurrent pneumonia with formation of pneumatoceles. "The link between STAT3 expression and IL-17A and IL-17F production was also demonstrated in humans in the context of autosomal dominant hyper-IgE syndrome (HIES, also called Job’s syndrome)." (PMID 29048384, 2017).
Bacteroides infection (1 paper, 2022). "In Bacteroides infection, IL-17A is significantly increased and helps disrupt the intestinal barrier." (PMID 35221923, 2022).
behavioral disorders (1 paper, 2025). "Prenatal imprinting to interleukin 17A (IL-17A) triggers behavioral disorders in offspring." (PMID 39384965, 2025).
Blindness (1 paper, 2023). Blindness is the condition of lacking visual perception defined as a profound reduction in visual perception. "Hence, IL-17A could be a potentially novel therapeutic target for retinal neovascularization, which can cause blindness in multiple ocular diseases." (PMID 36675261, 2023).
B‐cell acute lymphoblastic leukaemia (1 paper, 2018). "Recently, a study also suggested that IL‐17A activates AKT signalling in B‐cell acute lymphoblastic leukaemia." (PMID 29689643, 2018).
cerebral edema (1 paper, 2019). "In addition to elevated IL-10 and IL-17A, patients with gram-positive shunt infection had elevated levels of VEGF, a potent mediator of vascular permeability associated with cerebral edema and neutrophil migration in the CNS." (PMID 30626412, 2019).
chronic allograft nephropathy (1 paper, 2022). "Other studies have reported that TH17 cells or circulating IL-17A are elevated in patients with acute transplant rejection and that persistent elevation in TH17 cells was found in patients with chronic allograft nephropathy." (PMID 35422004, 2022).
Ciliopathies (1 paper, 2022). "Moreover, pathways related to Cilia function and development, such as Primary cilium development, Cilium assembly, and Ciliopathies, were the most regulated pathways by IL-17A, involving 105 cilia-related-genes." (PMID 35773318, 2022).
collagenous colitis (1 paper, 2014). A type of microscopic colitis of unknown etiology. "There was significantly increased production of the proinflammatory cytokines IFN-γ, IL-17A, IL-6, and IL-1β in the presence of CM generated by culture of denuded biopsies (DNB-CM) from the colon of collagenous colitis patients, compared to DNB-CM from noninflamed controls." (PMID 25332518, 2014).
contagious pleuropneumonia (1 paper, 2020). A pleuropneumonia of cattle and goats caused by species of mycoplasma. "There are several reports documenting an increased population of IL-17A producing T cells and secretion of IL-17A in pigs, such as the presence of Actinobacillus pleuropneumoniae specific Th17 cells [CD4+CD8αdimIL-17A+] in the blood and lungs of porcine contagious pleuropneumonia infected pigs." (PMID 33391267, 2020).
cutaneous sarcoidosis (1 paper, 2020). "Here, we focused on cutaneous sarcoidosis and also report a significant increase in IL26 gene expression whereas the gene expressions of IL22 and IL17A were not affected." (PMID 33057074, 2020).
Duodenal polyposis (1 paper, 2025). Presence of multiple polyps in the duodenum. "In conclusion, our findings indicate that duodenal polyposis in FAP is associated with an increase in IL-17A(+)NKp44(−)ILC3s, predominantly localized in the epithelial area and marked by strong expression of epithelial retention markers." (PMID 40280932, 2025).
energy metabolism disorder (1 paper, 2022). "Our work elucidated a new mechanism of IL‐17A in PF from an energy metabolism disorder perspective, which enriched and complemented the current research." (PMID 36308405, 2022).
epididymitis (1 paper, 2023). Inflammation of the epididymis. "In the vivo experiments, levels of the proinflammatory cytokines IL-1α, IL-6, IL-17A, TNF-α, IL-1β, MCP-1, and GM-CSF, mRNA for MyD88 related genes, and the percentages of monocyte-derived DCs (Mo-DCs) were significantly elevated in mice with epididymitis." (PMID 37175545, 2023).